NGF (nerve growth factor)
Diseases named in the same sentence as NGF in open-access papers (continued):
Sharing a sentence is not in itself a finding about the gene and the disease.
cancer (continued). "This insight points to the potential utility of SDF_1A and B_NGF as biomarkers in the pathogenesis of SCLC, highlighting the need for further investigation into their roles and mechanisms within this specific cancer type." (PMID 39132165, 2024). "Anti‐NGF antibodies, TRKA inhibitors, and NGF‐targeted siRNA delivered via nanoparticles have shown promise in reducing cancer growth and metastasis in animal models, and these approaches are advancing to clinical trials." (PMID 39492832, 2024). "For instance, OSCC cells facilitate TME innervation by secreting NGF, which prompts nociceptive nerves to secrete CGRP and promote cancer growth." (PMID 39492832, 2024). "NGF, which is highly expressed by OSCC cells, can activate its two receptors TrkA and NGFR, contributing to PNI, cancer pain, and metastasis." (PMID 38334648, 2024). "It inhibits inflammatory cytokines such as TNF-α, IL-6, and IL-1β, improves cognitive functions by regulating the NGF-BDNF-CREB signaling pathway, and shows antiproliferative effects on cancer cell lines like AGS, HT-1080, and HT-29." (PMID 39124930, 2024). "Various clinical studies have shown that anti-nerve growth factor (NGF) antibodies, bisphosphonates, or RANKL inhibitors can reduce the incidence and improve the management of cancer pain." (PMID 37007073, 2023). "A cascade of released substances follows, so that neurons release neurotransmitters, which in turn promote the secretion of NGF and BDNF from cancer cells." (PMID 36941697, 2023). "We found that NGF secreted by PanCa cells can mimic the effect of exogenous NGF, induce the autophagy of SCs, and then promote PNI via the proliferation of SCs and cancer cells and the outgrowth of nerve fibers." (PMID 35109895, 2022). "In a similar way, MMP9 was shown to regulate the activity of nerve growth factor (NGF)-induced transmembrane receptor tyrosine kinase A (TrkA), EGFR/HER, and insulin receptor (IR) signaling in cancer cells." (PMID 35406619, 2022). "The binding of NGF to NGFR/p75NTR leads to the activation of NF-kB or JNK, which mediates opposite effects on survival and apoptosis of both neurons and cancer cells, respectively." (PMID 36354700, 2022). "This trimeric complex plays critical roles in ligand-induced activation of several RTKs, including the EGFR, insulin receptor (IR), the nerve growth factor (NGF) TrkA receptor, and TOLL-like receptors (TLRs), all of which are upregulated in cancer." (PMID 35326525, 2022). "The data provided here is a comparison of a normal and a cancer cell line in response to the following growth factors, EGF, TGFα, TGFβ-1, VEGF, and NGF, and a specific inhibitor of Akt, MK2206." (PMID 35681586, 2022). "Cancer cells release inflammatory mediators as well as pro-angiogenic factors, including fibroblast growth factor 2 (FGF-2), SCF, and nerve growth factor (NGF), thus activating vascular epithermal growth factor (VEGF) and SCF/c-KIT signaling among others." (PMID 35216365, 2022). "NGF/TRKA signalling (via PI3K/AKT and MAPK/ERK pathways) increases the expression of oncoproteins such as survivin and β-catenin, in cancer cells, and these two proteins are also upregulated in EOC." (PMID 33081077, 2020). "And, NGF binds TrkA to induce phosphorylation of TrkA for activation of intracellular signalling pathways (MAPK, PI3K and so on), resulting in cancer progression." (PMID 32294802, 2020). "Among them, NGF and BDNF are the most important NTs studied in the context of reproduction and cancer." (PMID 31608227, 2019). "The p75NTR, NGF/TrkA (for ESCC), and BDNF/TrkB (for GC) have been extensively researched in these cancers in an effort to develop better predictive markers." (PMID 30741921, 2019). "BD specifically upregulated tRNA Charging, while RG exclusively activated NGF Signaling and SPINK1 General Cancer Pathway." (PMID 31781116, 2019).
cancer (continued). "In AMP cancers, we highlight RAS, NGF and EGFR and axon guidance signaling pathways, since identified miRNAs modulate the expression of target genes with overlapping roles in all three pathways." (PMID 31150430, 2019). "In line, NGF promotes angiogenesis by TrkA-mediated activation of PI3K and matrix metalloproteinase 2 (MMP2) in breast, ovarian, hepatocellular cancers." (PMID 31812953, 2019). "Based on the ingenuity pathway analysis (IPA), these targets are significantly enriched in many canonical cancer-related pathways and bioterms, including the molecular mechanism of cancer, ERK/MAPK signaling, PI3K/AKT signaling, and NGF signaling." (PMID 29074968, 2017). "As a control for the selectivity on cancer cells, we further tested MG-2477 on all-trans retinoic acid (RA) differentiated NB8 and NB15 cells and on NGF-differentiated PC12 cells." (PMID 28415610, 2017). "Seed sequences for miRNA binding where also identified in signaling pathways and regulatory molecules such as Molecular Mechanisms of Cancer, HGF, NGF and ErbB, which promote the growth and survival of macrophages." (PMID 27119502, 2016). "Also the fact that NGF and AGM levels stay high seems realistic: NGF levels are higher in inflammation and some studies report that semaphorin 7A and netrin-1 levels are significantly elevated in patients subject to chemotherapy and some kinds of cancers, respectively." (PMID 26861829, 2016). "After ignoring this cross-talk, the next best cross-talk in terms of gene count is between “signalling by NGF” with the same set of pathways as in CM i.e. “signalling by FGFR in disease”, “signalling by EGFR in cancer” and “signalling by PDGF”." (PMID 26558755, 2015). "C6 cancer cell lines were exposed to doses of CAPE; DNA fragmentation and MAPKs and NGF/P75NTR levels were then determined." (PMID 24997497, 2014). "While it appears that NGF can affect both VGSC expression and cancer cell motility, further work is required to clarify the connection between the two effects and the nature of the associated receptor and downstream signalling mechanisms." (PMID 24493753, 2014). "In support of this hypothesis, preventive treatment with an antibody that sequesters NGF, administered when prostate tumor-induced pain and bone remodeling were first observed, blocked this ectopic sprouting and significantly inhibited the development and severity of cancer pain." (PMID 22640953, 2012). "Interestingly, sustained administration of an anti-NGF sequestering therapy blocked the pathological sprouting of sensory and sympathetic nerve fibers, the formation of neuroma-like structures, and significantly attenuated the generation and maintenance of cancer pain in this model." (PMID 22640953, 2012). "The majority of cancer cells and nerve tissues showed distinct immunostainings of TrkA, P75NTR, and NGF localized to the cytoplasm." (PMID 21386984, 2011). "In addition to NGF and GDNF, BDNF increases cancer cell invasion and chemotaxis toward nerves through TrkB‐mediated activation of phosphoinositide 3‐kinase (PI3K)/AKT and mitogen‐activated protein kinase (MAPK)/ERK signaling pathways." (PMID 41556039, 2026). "Cancer cells actively produce and secrete neurotrophic factors, notably nerve growth factor (NGF), brain-derived neurotrophic factor (BDNF), neurotrophin-3 (NT-3), and glial cell line-derived neurotrophic factor (GDNF)." (PMID 41009819, 2025). "There is overexpression of receptors TrkA and p75 on the surfaces of cancer cell lines like MDA-MD-231 and MCF-7; owing to such overexpression and the fact that NGF is highly specific to its receptors, these complexes can be potentially used as molecular markers." (PMID 41210918, 2025). "Chemokines such as CCL2, or endocrine hormones and neurotrophic factors, including nerve growth factor (NGF) and glial-derived neurotrophic factor (GDNF), are known to promote both in vitro and ex vivo culture models, suggesting that cancer cells surrounding nerves exhibit increased survival." (PMID 40427098, 2025).
cancer (continued). "Other cancers may secrete EVs that contain brain-derived neurotrophic factor (BDNF) and nerve growth factor (NGF)." (PMID 40722712, 2025). "Similarly, colon cancer-derived exosomal miR-21-5p suppresses Von Hippel-Lindau expression in SCs, stabilizing hypoxia-inducible factor-1α to elevate NGF secretion, which reciprocally activates ERK signaling and promotes PNI in cancer cells." (PMID 40421086, 2025). "NGF in the TME plays a multifaceted role, impacting various aspects of the immune response and playing a role in drug resistance in various types of cancers, contributing to the growth of inherently resistant populations and influencing the response of initially drug-sensitive cells." (PMID 38392180, 2024). "One of the most well-studied NTs is the nerve growth factor (NGF), which binds to its specific receptor, tropomyosin-related kinase A (TrkA), expressed on various types of cancer cells, including those derived from the brain, prostate, breast, and pancreas, among others." (PMID 38392180, 2024). "In the context of cancer, NRP1 inhibitors would be expected to suppress NGF-evoked pain and VEGF-A–mediated angiogenesis in tumors, although impaired wound healing could be a liability." (PMID 39589827, 2024). "Moreover, salivary ACC-derived exosomes stimulate fibroblasts to produce NGF, eventually leading to PNI occurrence and cancer progression." (PMID 39906323, 2024). "Additionally, a significant number of drugs targeting neuro-cancer signaling pathways are currently under development, including NGF (Nerve Growth Factor) inhibitors, Glutamate release inhibitors, and Voltage-Gated Sodium Channel (VGSC) inhibitors." (PMID 38567163, 2024). "We recently showed that nerve growth factor (NGF) drives MEC differentiation during development, and upregulated neurotrophin signaling in human MEC after irradiation for cancer is associated with stress-induced plasticity and lack of regeneration." (PMID 39217171, 2024). "Many years have indeed passed from the discovery of nerve growth factor (NGF) in the early 1950’s to the studies concerning its role in non-neuronal as well as cancer cells." (PMID 36941697, 2023). "In addition to NGF, tumors also secrete other neurotrophic substances such as brain derived neurotrophic factor (BDNF), which is closely related to cancer pain." (PMID 37007073, 2023). "There is increasing evidence that nerve growth factor (NGF) and its receptors, the neurotrophic receptor tyrosine kinase 1 (NTRK1/TrkA), the common neurotrophin receptor (NGFR/p75NTR) and the membrane receptor sortilin, participate in cancer growth." (PMID 35457078, 2022). "It has been shown that nerve growth factor (NGF) potentiates neoaxonogenesis and that systemic or local administration of NGF receptor inhibitors or antibodies against NGF reduces the density of nerves in cancer tissues, including breast and pancreas." (PMID 34204103, 2021). "NGF acts not only on the central and peripheral nervous systems but also on non-neuronal tissues and cancer cells." (PMID 34283074, 2021). "In neurons, nerve growth factor (NGF) stimulates ETV4 expression through the ERK1/2 pathway, while it is regulated by both the ERK1/2 and SAPK/JNK pathways in cancer cells." (PMID 34381375, 2021). "The roles of NGF and its receptors (TRKA and p75NTR) in cancer are well established." (PMID 33392191, 2020). "NGF/TRKA and BDNF/TRKB are the main NTs studied in the context of cancer." (PMID 31608227, 2019). "The ACh-NGF axis is a positive feedback loop which promotes the abnormal innervation observed in the TME and consequently contributes to gastrointestinal carcinogenesis, regulating both cancer cells growth and peritumoral TME remodeling." (PMID 30741921, 2019). "A cooperative effect of tBHQ and Tm on NGF and HO-1 expression was also observed in normal human astrocytes (NHAs), suggesting that ATF4 and Nrf2 cooperation is not limited to cancer cells." (PMID 30959808, 2019).
cancer (continued). "The source and mechanism of NGF induction in pain has not been clearly defined, although it is not thought to be produced by cancer cells." (PMID 31578352, 2019). "Therefore, inhibition of proNGF, NGF, or NGFR has been proposed as therapeutic stratagems for human malignant tumors." (PMID 28679437, 2017). "The observation that NGF-exposed naive cells do not generate cancer cell phenotypes argues against a primary role of NGF in promoting cancer cell generation." (PMID 27439311, 2016). "In this report, we demonstrate for the first time that NGF induces TrkA/CD44 interaction independent of TrkA phosphorylation in cancer cells." (PMID 25840418, 2015). "In CM, NGF signalling genes display a dense nature of co-membership with other signalling events and maximally co-membered (n = 37) with “signalling by FGFR in disease”, “signalling by EGFR in cancer” and “signalling by PDGF”." (PMID 26558755, 2015). "Also, further study is needed to elucidate if the relationship between angiogenesis, NGF, TRKA and VEGF is also present in other types of cancer." (PMID 25296882, 2014). "Increasing evidence suggests that NGF and HO1 are involved in tumorigenesis and could therefore be possible therapeutic targets of human malignant tumors." (PMID 24180625, 2013). "However, the relationship between NGF and HO1 and the role of HO1 in cancer progression is still unclear in BRCA." (PMID 24180625, 2013). "Additionally, nerve-derived NGF enhances perineural invasion (called PNI or axon-guidance activity) and ultimately results in the irritative and disabling symptoms of certain types of malignancies." (PMID 40783715, 2025). "Additionally, TGF-β has been shown to modulate the release of pain-related molecules, including nerve growth factor (NGF) and other neurotrophic factors, which can sensitize nociceptive pathways and contribute to the development of hyperalgesia in cancer patients." (PMID 40579593, 2025). "In addition, oral tongue SCC research revealed that NGF expression in cancer cells correlates with PNI and lymph node metastasis." (PMID 39906323, 2024). "Identifying the antinociceptive efficacy of vesencumab highlights an opportunity to repurpose a biologic developed for cancer for the treatment of chronic pain, facilitating the development of a nonopioid therapeutic targeting NGF signaling through its coreceptor identified in this study." (PMID 39589827, 2024). "Given the potential role of NGF in CSC behavior, it has been suggested as a potential therapeutic target so that modulating NGF signaling pathways could be explored as a strategy to target CSCs and improve the effectiveness of cancer treatments." (PMID 38392180, 2024). "Studies have suggested that before cancer cells migrate to peripheral neurons, SCs migrate to pancreatic or colon cancer cells through the NGF-TrkA-p75NTR signaling pathway, but do not migrate to benign cells, so activated oncogenic SCs are likely to construct a pathway to cancer cells." (PMID 36900158, 2023). "Previous studies have presented neurotransmitters and neurotrophins (e.g., substance P, nerve-growth factor (NGF) and brain-derived neurotrophic factor (BDNF)), chemokines (e.g., CX3CL1 and CCL2), extracellular vesicles, and Schwann cells as key players in cancer–nerve crosstalk." (PMID 35565690, 2022). "In the development of anti-cancer drugs, the presence or absence of NGF must be taken into account, as despite the inactivation/antagonism of the P2Y2 receptor, NGF may nevertheless stimulate cell proliferation." (PMID 32545311, 2020). "However, the use of anti-NGF antibodies in fighting cancer progression in humans has not yet been tested." (PMID 33322770, 2020). "Thus, considering that in other cancers PGE2 is known to modulate VEGF levels, we evaluated here whether such NGF-mediated increases in VEGF were connected to the COX-2/PGE2 signaling pathway." (PMID 31817839, 2019).
cancer (continued). "Given NGF’s role in MKP expansion and MK survival, NGF could be evaluated as a protective agent against chemotherapy-induced progenitor cell death in cancers with no TrkA involvement." (PMID 30808933, 2019). "Following pathway analysis of the seven cancer types, we have found ten common cancer – related pathways such as axon guidance, cell cycle checkpoints, signaling by FGFR, DNA repair, DNA replication, opioid signaling, HIV infection, cell cycle, mitotic signaling by NGF, and signaling by EGFR." (PMID 29020948, 2017). "Neurotrophins (Nerve Growth Factor (NGF), Brain-Derived Neurotrophic Factor (BDNF), and Neurotrophin-3 (NT-3)), as well as their cell surface receptors (p75, TrkA, TrkB, and TrkC) are validated targets for therapeutics in a variety of pathologies ranging from cancer to neurodegeneration." (PMID 24603864, 2014). "A striking similarity of this novel receptor signaling platform was reported by us for nerve growth factor (NGF) TrkA receptors, insulin receptors, cell surface TOLL-like receptor-4 (TLR-4) and intracellular TLR-7 and -9; these receptors are known to play major roles in cancer." (PMID 26932374, 2014). "Furthermore, NGF and pro-NGF may induce a state of quiescence in cancer cells, leading to cells not actively dividing, which are less susceptible to drugs that target rapidly dividing cells." (PMID 38392180, 2024). "The insights gained from unraveling the intricate interactions of NGF, inflammatory molecules, and the TME may pave the way for the development of precision therapies, enabling the exploitation of its dual nature for more effective and personalized cancer interventions." (PMID 38392180, 2024). "In addition, because we provide a method that allows direct coculture of neuronal precursors with cancer cells, the continuous exposure to secreted factors, rather than discrete NGF addition, may sustain a more robust and continuous response." (PMID 37046688, 2023). "In addition, we demonstrated that EGF show different functionality than NGF or GDNF and that EGF is a new potential analgesic modulator in the process of pain sensitization, a result of importance not least in the light of the increased use EGFR blockers for therapeutic cancer treatment." (PMID 21187008, 2010). "Similarly, in NGF-treated PC12 cells top biological functions deal with the overall topics on cellular growth and proliferation (37 genes), cell-to-cell signalling and interaction (31 genes), molecular transport (30 genes), cancer (30 genes), cellular movement (29 genes) and others." (PMID 19239705, 2009). "For instance, studies in nerve growth factor (NGF) has reported that this factor acts not only on the PNS and CNS but also on nonneuronal and cancer cells." (PMID 36072337, 2022). "With respect to the action of NGF, most of these studies have not been done in EOC or even in cancer; but on neuronal models." (PMID 28245631, 2017). "Although chemokines and neurotrophic factors with chemoattractive properties such as NGF, GDNF, artemin, or neurturin have long been studied in the context of NI in PDAC, the cytoskeletal adaptations of cancer cells during their nerve-directed migration have not been in the focus." (PMID 37607005, 2023). "Recent progress in the Nerve Growth Factor (NGF) research has shown that this factor acts not only outside its classical domain of the peripheral and central nervous system, but also on non-neuronal and cancer cells." (PMID 27439311, 2016).